CHD1 (chromodomain helicase DNA binding protein 1)
Diseases named in the same sentence as CHD1 in open-access papers (continued):
Sharing a sentence is not in itself a finding about the gene and the disease.
nephrolithiasis (1 paper, 2016). The presence of a calculus in the pelvis of the kidney; this is most often composed of mineral salts and proteins. "Our study is the first to put forward the association between CHD1 rSNP (rs16260) and nephrolithiasis by seeking linkages among the risky genotypes (CA and CC) and serum calcium and 24 h urinary magnesium levels." (PMID 27733975, 2016). "Previous studies have shown that SNPs in the CHD1 gene might have altered the risk of nephrolithiasis development." (PMID 27733975, 2016). "Thus CHD1 rSNPs in conjunction with renal cell injury, caused by oxalate crystals, may contribute to the development of nephrolithiasis." (PMID 27733975, 2016). "Further large population-based genome-wide association studies (GWAS) are necessary to clarify the potential function of CHD1 rs16260 in the progression of nephrolithiasis." (PMID 27733975, 2016).
Obesity (1 paper, 2021). Accumulation of substantial excess body fat. "On the other hand, genes up-regulated with pregravid obesity enriched to GO terms associated with transcriptional regulation (JMJD1C, CHD1, HIF1A, TCF25, and KLF6)." (PMID 33912153, 2021).
periodontitis (1 paper, 2024). An acute or chronic inflammatory process that affects the tissues that surround and support the teeth. "In turn, neutrophils isolated from periodontitis were characterised by high expression of CHD1 and JMJD2A, which corresponds with the in vitro model of neutrophils exposed to IL-10." (PMID 38745328, 2024). "High density within CHD1 as well as JMJD2A is observed in periodontitis which accurately corresponds with the in vitro model- neutrophils exposed to IL-10." (PMID 38745328, 2024). "Neutrophils isolated from periodontitis that respond correctly to IL-10 were characterised by high CHD1 and JMJD2A expression (ICC and ChiP-Seq H3K4me3 results), opposite to sepsis-derived neutrophils, with no changes within these enzymes." (PMID 38745328, 2024).
Pleural effusion (1 paper, 2025). The presence of an excessive amount of fluid in the pleural cavity. "The reason for this remains unclear, but it may relate to the distinct biology of CAMA1, which was derived from a pleural effusion and shows evidence of CHD1 inactivation through promoter methylation." (PMID 41226317, 2025).
Pseudomonas infection (1 paper, 2012). Infections with bacteria of the genus pseudomonas. "Thus, Chd1-mutant flies show similar susceptibility to Pseudomonas infection as the Imd-pathway mutant DreddEP1412." (PMID 22912810, 2012).
Sepsis (1 paper, 2024). Sepsis is defined as life-threatening organ dysfunction caused by a dysregulated host response to infection. "Especially, the high signal of MLL1, SETD1A, but also CHD1 and JMJD2A is observed in the course of sepsis which did not correlate with LPS stimulation resulting in MLL1 and STED1A high signal only." (PMID 38745328, 2024).
Snijders Blok-Campeau syndrome (1 paper, 2023). Snijders Blok-Campeau syndrome (SNIBCPS) is an autosomal dominant neurodevelopmental disorder characterized by global developmental delay with impaired intellectual development and delayed speech acquisition. "Pathogenic variants in CHD proteins contribute to the development of a range of neurological disorders, such as CHD1 in Pilarowski-Bjornsson syndrome, CHD3 in Snijders Blok-Campeau syndrome (SNIBCPS), CHD4 in Sifram-Hitz-Weiss syndrome, CHD7 and CHD8 in Autism Spectrum Disorder (ASD)." (PMID 36647159, 2023).
tumor (59 papers, 2011 to 2026). "Responders were enriched for MMR-d, BRCA1/2 loss, high TIL density, CDK12 loss, ATM or CHD1 alterations, underscoring the predictive value of a broad tumor-based immunogenic signature." (PMID 40806607, 2025). "Another example is the co-loss of MAP3K7 and CHD1, two tumor suppressor genes, which coordinate to drive disease aggressiveness." (PMID 40840524, 2025). "The current study elaborated that CHD1 was coregulated by circLDLR and miR-449b-5p, and furthermore, CHD1 deficiency attenuated the tumor-promoting effects induced by circLDLR in GC." (PMID 38665782, 2024). "CHD1 depletion significantly suppressed tumor growth in PTEN-deficient xenograft models, consistent with earlier observations in LNCaP xenograft tumors." (PMID 36776288, 2023). "They showed that loss of CHD1 induces the transcription factors of GR, BRN2, TBX2, and NR2F1, which are required to promote tumor heterogeneity and resistance to AR inhibitors in CHD1-deficient tumors." (PMID 36776288, 2023). "From a clinical perspective, the loss of CHD1 has been found to correlate with higher Gleason grade, tumor stage, and postoperative biochemical relapse (BCR) in a cohort of more than 2000 PCa patients and suggested as a predictor for poor prognosis." (PMID 33414516, 2022). "Of relevance, CHD1 mutation was shared among all subclones while two main subclones captured discrete subsets of truncal mutations from the original primary tumor (T1) and stably transmitted across PDX passages and organoid samples." (PMID 33602919, 2021). "The tumor-suppressor gene CHD1 encodes a chromatin remodeler, and inactivating mutations occurs in 7–10% of human PCa." (PMID 34502458, 2021). "It will be of interest to explore the potential role of Chd1 in transcription-associated DNA break repair in other cell types, both in physiological stem/progenitor cells as well as in proliferating tumor cells." (PMID 34381042, 2021). "Loss of CHD1 has been reported in 15% of HSPCs and 17% of CRPCs and CHD1 loss has been implicated in PC cell chromatin rewiring with tumor-suppressing functions and increased sensitivity of PC tumors to DNA damage." (PMID 34283056, 2021). "PCA carrying a CHD1 deletion is associated with early recurrence of serum prostate specific antigen, a high Gleason grade, advanced tumor stage and increased cell proliferation." (PMID 31222142, 2019). "Univariate analysis for overall survival and disease-free survival showed that the tumour location in the head, lymph nodes metastasis, long-DM and methylation of CHD1 promoter were a significant risk for shorter survival." (PMID 29273724, 2017). "In addition, loss of the chromatin-remodeling protein CHD1, in about 20% of tumors, reprograms the AR cistrome into an oncogenic state and contributes to tumor progression." (PMID 40840524, 2025). "Interestingly, in the face of therapeutic challenge with ARSI, CHD1 loss seems to then allow alternative master transcription factors to dominate, leading to AR-independent mechanisms of tumor growth." (PMID 36212399, 2022). "Here, loss of JUP, presumably contributing to reduced tumor cell cohesion by disturbing desmosome and adherens junction assembly, might additionally promote the more metastasis‐prone phenotype of CHD1‐deleted cancers within the ERG‐negative subset." (PMID 33533127, 2021). "The study of some of these patients with hormone-naïve and castration-resistant tumor samples established 17% CHD1 loss in tumor biopsies; CHD1 loss and/or SPOP mutations were associated with a higher response rate to Abiraterone and a longer time on Abiraterone." (PMID 31366128, 2019). "Chd1 has been identified as a PCA tumor suppressor, and loss of CHD1 promotes PCA aggressiveness." (PMID 31222142, 2019).
tumor (continued). "CHD1 loss has previously been found to be enriched in mCRPC patients with primary resistance to abiraterone and enzalutamide based on analysis of circulating tumor cells, and low CHD1 expression has been reported to be associated with shorter response to enzalutamide but not abiraterone." (PMID 40229848, 2025). "Previous studies have indicated that CHD1 supports tumor growth by modulating metabolic genes such as HK2 and LDHA, with its inhibition suppressing proliferation and inducing apoptosis, particularly in PTEN-deficient models." (PMID 41249788, 2025). "Predominantly, members of the CHD subfamily are associated with tumor suppression, however, some members, such as CHD1 and 8, are reported to exhibit both tumor-suppressive and pro-oncogenic functions depending on the context." (PMID 41278204, 2025). "The 22Rv1∆ex29/∆ex29 cells showed significantly reduced tumor formation compared to the 22Rv1WT/fs cells, indicating the C-terminal of CHD1 has tumor-suppressive effects." (PMID 41168190, 2025). "This study elucidates the role of IDRs in CHD1-mediated condensation and highlights their importance in tumor suppression." (PMID 41168190, 2025). "In PTEN-deficient cancers, AKT activation-induced GSK3β suppression results in the disruption of CHD1 proteolysis and aberrant accumulation of the CHD1 protein, which contributes to tumor development and tumor microenvironment (TME) remodeling." (PMID 36776288, 2023). "It is also worth determining if CHD1 inhibitors synergize with AR or GR inhibitors in suppressing CRPC tumor growth and progression." (PMID 36776288, 2023). "Despite these encouraging factors, it is worth noting that tumor progression was rarely observed in some Pten/Chd1 double-knockout mice." (PMID 36776288, 2023). "The list of potential tumor suppressor hits included both known factors, such as Ezh2 and Tle4, as well as novel candidates, including Kdm5c, Pcgf3, Chd1 and Pbrm1." (PMID 36631623, 2023). "Given that CHD1 inhibition sensitizes tumor cells to DNA-damaging agents, the combination of CHD1 inhibitors and DNA-damaging therapies should be tested in preclinical and clinical studies as well." (PMID 36776288, 2023). "Through interacting with different genetic alterations, CHD1 possesses the capabilities to exert oncogenic or tumor-suppressive functions in context-dependent manners." (PMID 36776288, 2023). "CHD1 knockdown reduced cell proliferation, impaired tumor growth, and prolonged the overall survival of mice in PTEN-deficient LNCaP-derived xenograft models." (PMID 36776288, 2023). "Control and CHD1-KD cells were subcutaneously injected into immunodeficient mice and potential effects of the CHD1-KD on xenograft primary tumor growth and spontaneous metastatic spread were analyzed." (PMID 33414516, 2022). "In particular, CHD1 is critical for double-strand break (DSB) repair via homologous recombination, so decreased CHD1 expression leads to genomic instability and hence tumor progression." (PMID 33414516, 2022). "In sharp contrast to our in vivo findings, in vitro assays for tumor cell proliferation and metastatic properties rather indicated less metastatic potential of CHD1-KD PCa cells." (PMID 33414516, 2022). "The present study confirms and considerably expands a previous publication from our group showing a correlation of CHD1 deletion with unfavorable tumor phenotype and early BCR." (PMID 33414516, 2022).
tumor (continued). "Overall, high JUP expression was associated with adverse tumor features, while low JUP expression indicated poor prognosis in CHD1‐deleted patients." (PMID 33533127, 2021). "Tumour harbouring oncogenic ETS fusion (ETS+) produced more inter-chromosomal rearrangements whereas tumour with a deletion of CHD1, a putative tumour suppressor gene, showed an excess of intra-chromosomal chained rearrangements." (PMID 30805029, 2019). "Loss of CHD1 promotes PCA aggressiveness and is associated with early recurrence of serum prostate specific antigen, a high Gleason grade, advanced tumor stage, and increased cell proliferation." (PMID 31222142, 2019). "mRNA instability and down-regulation of the gene in mesenchymal tumor cells were shown to occur as a result of the regulatory sequence of CHD1 gene." (PMID 27733975, 2016). "Overall, these studies strongly suggest a concerted function between Paf1 and CHD1 proteins in regulating gene expression, thereby affecting the process of cell cycle progression, differentiation or tumor development." (PMID 22046413, 2011). "We discover that loss of CHD1 and MAP3K7 (encoding TAK1) potentiates the transcriptional response to IFN-γ, thereby creating an acquired vulnerability by sensitizing cancer cells to tumor-reactive T cells." (PMID 41564866, 2026). "Specifically, they found that CHD1 localizes to chromatin-containing canonical AR binding sites, but CHD1 loss causes AR to redistribute to HOXB13-enriched sites, which drives a unique AR transcriptome that contributes to the tumor formation." (PMID 36776288, 2023). "In addition, our in vitro assays revealed a contrary phenotype of the tumor cells in vitro (decreased invasiveness and colony-forming capacity upon CHD1-KD )." (PMID 33414516, 2022). "Therefore, it appears that CHD1 acts as a tumor suppressor by preserving the integrity of the AR cistrome, whereas its loss leads to the reprogramming of the AR cistrome and an altered AR-associated transcriptome." (PMID 36212399, 2022). "After comparable growth periods, the CHD1-KD increased the tumor take rate of ARCAP-M xenografts (five of seven mice in the shNeg group and seven of seven mice in the shCHD1 group developed tumors) and caused significantly higher primary tumor weights in PC-3 xenografts." (PMID 33414516, 2022). "We did not observe differences in SPOP mutation or CHD1 loss frequency by tumor BRCA2 status, although these genes have been implicated in impaired HR repair." (PMID 35715489, 2022). "CHD1 as tumor suppressor gene, is currently rare in tumor resistance mechanisms." (PMID 33663617, 2021). "A major insight from our characterization of how CHD1 loss promotes enzalutamide resistance is the role of an altered chromatin landscape in establishing a cell state that enables more rapid adaptation to environmental stresses, such as antiandrogen therapy than can occur in CHD1-intact tumor cells." (PMID 32220301, 2020). "Patients in the lowest quartile of tumor CHD1 expression had a significantly shorter time to progression on either enzalutamide or abiraterone compared with the patients in the highest quartile (p = 0.0261), supporting the predictions from the preclinical findings." (PMID 32220301, 2020). "Mouse CHD1 is required for the maintenance of stem cell pluripotency while human CHD1 may function as a tumor suppressor." (PMID 23533627, 2013). "However, combined knockdown of MAK3K7 and CHD1 led to larger tumor volumes and shorter survival." (PMID 27145457, 2016).
tumor (continued). "Our prior studies using multiple GEM models demonstrated that CHD1 is involved in the inflammatory response and plays a crucial role in modulating the TME via promoting MDSC infiltration and suppressing tumor-infiltrating lymphocytes (TILs)." (PMID 36776288, 2023). "The reduced expression of OXPHOS and mitochondrial translation components also correlated well with the changes in epithelial-mesenchymal transition (EMT) markers, E-cadherin (CHD1), and vimentin (VIM) in the ER/PR(+) tumor biopsies." (PMID 36119536, 2022). "The number of circulating tumor cells (CTC) in the mouse blood was slightly, but insignificantly increased after CHD1-KD in both xenograft models." (PMID 33414516, 2022). "A significant role in the recruitment of MDSCs to PC has also been assigned to chromodomain helicase DNA-binding protein 1 (CHD1), an essential tumor suppressor." (PMID 35860573, 2022). "The tumour-derived L46R substitution that maps to the F1 lobe strongly disrupted the interaction with the PAFC and CHD1 but only had a partial effect on VPRBP." (PMID 34424918, 2021). "While in ERG+ rearranged tumours, the earliest homozygous deletions appeared in region chr5:55-59 Mb in ERG− cancers, losses at chr5:60-100 Mb, covering the well-known affected gene CHD1, were reported." (PMID 31275657, 2019). "C5 tumors maintained the key characteristics of the original tumor for at least 6 passages and are AR+, PSMA+, ERG+, PTEN−/−, CHD1+/−." (PMID 30510249, 2018). "Those genes reportedly involved in tumor cell adhesion, gap junction and ECM, such as CHD1, Cx26, Cx43, Cx45, COL1A1, FN1, LOX, ITGB1 and LAMA4, were also up-regulated following 3D cultures." (PMID 26055407, 2015). "On one hand, tumor-intrinsic epigenetic factors such as SIRT1, CHD1, and MAP3K7 can determine whether a tumor is permissive or resistant to VSV infection, making them promising biomarkers for patient stratification." (PMID 41294689, 2025). "Given that CHD1, CDH2, MMP2 and MMP9 play an important role in the process of EMT, we hypothesize that CCT8 mediate tumor metastasis through EMT." (PMID 37928427, 2023). "CHD1 contributes to immunosuppressive TME by promoting MDSCs and suppressing tumor-killing T cells." (PMID 36776288, 2023). "Tumor cells from conventional (2D) cell culture were also not used for RNA-seq since the pro-metastatic effect of the CHD1-KD observed in vivo was not reflected in vitro." (PMID 33414516, 2022). "Furthermore, the analysis indicated that the CHD1 is an oncogene and that PDS5B is a tumor suppressor." (PMID 31222142, 2019). "Given that doxorubicin, a commonly used anti-cancer drug, enhances nucleosome turnover, the identification of Chd1 in directing nucleosome turnover provides a mechanistic basis for its tumor suppressor role and may indicate the molecular basis for carcinogenesis in the absence of Chd1." (PMID 24737864, 2014).